FOXP3 (forkhead box P3)
Diseases named in the same sentence as FOXP3 in open-access papers (continued):
Sharing a sentence is not in itself a finding about the gene and the disease.
tumor (continued). "Strong positive correlations were found between frequencies of FoxP3+ Tregs and FoxP3+Helios+ Tregs with frequencies of various immune checkpoint-expressing CD4+ T cells in the tumor microenvironment (TME)." (PMID 36146549, 2022). "The density of FoxP3- CD4+ helper T cells, CD137+ CD8+ cytotoxic T cells, and CD137+ CD4+ T cells seemed to be numerically higher in the tumor margin than in the stroma or center." (PMID 36237314, 2022). "In order to evaluate determinants of benefit with PD-1/PD-L1 inhibitors, we performed multimodal analysis including genomics (through NGS panel tumour-only with 431 genes) and the immune microenvironment (using CD3, CD8, FOXP3 and PD-L1 antibodies)." (PMID 36613564, 2022). "In “inflamed” tumours, defined by high intraepithelial CD8+ T cell infiltration, the opposite was the case and high stromal FoxP3+ T cell densities were a positive prognostic factor (p = 0.048)." (PMID 35140715, 2022). "The results shows that the best explaining factor was tumor HPV, the second factor was the TIL Foxp3-positive level, and the third factor was age of the patient." (PMID 35326661, 2022). "To confirm the results obtained by comprehensive bioinformatics analysis, we performed immunohistochemical staining of tumor tissues from 80 patients with PTC and 18 patients with ATC for the M2 macrophage marker CD163 and the Treg marker Foxp3." (PMID 35222534, 2022). "A total of 83 PrBC and 89 EOBC were selected from our Institutional registry and subjected to tumor-infiltrating lymphocytes (TILs) profiling and immunohistochemistry for CD4, CD8, forkhead box P3 (FOXP3), and programmed death-ligand 1 (PD-L1) (clone 22C3)." (PMID 35892583, 2022). "FoxP3+ cell density levels correlated with those of CD8+ cells and were distinctly higher in “inflamed” tumours than in those classified as “immune-desert”." (PMID 35140715, 2022). "Tumor analysis revealed enhanced tumor infiltration of CD4+ and CD8+ T effector cells and lower numbers of CD4+Foxp3+ Treg." (PMID 35693776, 2022). "In the primary tumor, the expression of all 12 markers (CD8, CD68, Foxp3, CD11c, CD163, CD66b, CD56, CD20, PD-L1, VEGFR-2, Ki67, IFN-γ) in the PT region was lower than that in the TF region (p < 0.05)." (PMID 36195882, 2022). "In cellular experiments, we confirmed the high expression of FOXP3 in MUM2B and OCM-1A cell lines and that knockdown of FOXP3 markedly inhibited the proliferation of UM tumor cells." (PMID 36466923, 2022). "The overexpression of VISTA suppresses T cell activation while promoting the transition of naive T cells into FoxP3+ Treg cells, immunosuppressing TME in PDAC, and fostering tumor growth." (PMID 36499340, 2022). "In parallel, we used multispectral immunofluorescence to confirm the localization of the CD8+, CD4+, FOXP3+, CD31+, and F4/80+ populations within the tumor 15 days after Delta-24-ACT treatment." (PMID 35393952, 2022). "The immune cells within tumor microenvironment from all samples were confirmed to express CD4 and CD8 on immune cell membranes, and FOXP3 on nucleus of immune cells by IHC examination." (PMID 35963999, 2022). "In this study, we observed that miR‐192‐5p affects tumour EMT by regulating RB1, inducing the secretion of IL‐10 to promote FOXP3+Treg cell differentiation and PD‐1 expression on Tregs in the TME." (PMID 35969010, 2022). "IHC performed on tumor biopsies done before C2D1, showed that percentages of PDL1+ tumor cells, ratio of CD3+ on CD163+ cells and density of FOXP3+ cells were significantly higher in patients with DCB than without DCB." (PMID 35794623, 2022). "We compared levels of FoxP3+ and MKi67+CD8+ cell densities (counts/mm2) from >1000 baseline tumor samples from clinical trials and commercially available sources." (PMID 35558070, 2022). "Subsequently, the high GSH concentration in tumor cells triggers CPT release from PCPT, which not only provides anticancer cytotoxic effects but also decreases the expression of Foxp3 in Treg cells." (PMID 35953798, 2022).
tumor (continued). "FCM-NPs induced tumor-specific cell-killing CD8+ IFN-γ+ T cells, and reduced the number of CD4+ CD25+ Foxp3+ Treg cells simultaneously, promoting the anti-tumor immune response." (PMID 35251013, 2022). "Tumor ROIs of short-term survivors revealed a high expression of molecules correlated with immune suppression such as PD-1, PD-L1, CTLA4, LAG3, FoxP3, and CD25 compared to long-term survivors." (PMID 36685537, 2022). "Equally important, the fraction of peripheral blood CCR8+ Treg cells (approx. 40% of all FoxP3+ Treg cells) are phenotypically similar to tumor CCR8+ Treg cells and share many TCR clonotypes with tumor CCR8+ Treg cells." (PMID 35158783, 2022). "This demonstrated that in the stroma of PDLIM2-positive and PDLIM2-negative tumours the percentages of CD4+, CD8+ or Foxp3+ T cells present in all tissues and stroma were similar, regardless of PDLIM2 expression." (PMID 36531051, 2022). "High tumor infiltration of CD3, Foxp3 and CD68-positive cells predicted better twenty-year OS, with and without HPV stratification." (PMID 36289746, 2022). "Tumor hypoxia results in expression of CCL28, which promotes the recruitment of CD4+CD25+FOXP3+ Treg cells by binding to the corresponding receptor, CCR10, on Treg cells." (PMID 35759090, 2022). "This is the first study to report a direct and strong correlation between densities of CD163+ or FoxP3+ cells and densities of CD8+ cells combined in the tumor center (TC) and tumor invasive margin (IM)." (PMID 36551693, 2022). "Fourteen TIL populations from 14 tumour specimens were further characterized via flow cytometry for the markers: CD69, HLA-DR, T-bet, CD45RA, Ki67, CD39, PD-1, and FOXP3." (PMID 35158816, 2022). "CD4+ CD25+ Foxp3+ Tregs were the predominant immunosuppressive cells and conveyed the antitumour T cell effector functions in the subcutaneous CT26 tumour BALB/c mouse model used in this study." (PMID 35996405, 2022). "When the tumor was palpable, two doses of DT were injected to deplete FoxP3.Luci-DTR + Tregs and tumor growth was measured over time and survival monitored." (PMID 34423375, 2022). "Taken together these data indicate the oral administration of EcN(lpp-OVA) promotes the modification of the tumor infiltrating T cells population by enhancing the frequency of the OVA-specific CD8+ T cells and reducing the amount of FoxP3+ cells." (PMID 35847919, 2022). "Specifically, we analyzed CD4+/Foxp3+ T regulatory cells (T-regs), CD4+/Foxp3− helper T cells (Th-cells), CD8+ cytotoxic T cells (Tc-cells), CD20+ B-cells, CD68+ macrophages, and CK+ tumor cells." (PMID 35565427, 2022). "SBRT alone resulted at two weeks after treatment in increased tumor densities of CD3+ T cells, FoxP3+ Tregs, and CD204+ macrophages, and increased expression of genes associated with immunosuppression." (PMID 35055015, 2022). "From these HCC tumor samples, we evaluated the levels of infiltrated CD3+ and FoxP3+ cells as metrics for TIL-T cells and TIL-Tregs, respectively." (PMID 36352020, 2022). "Staining patterns of FOXP3, CD8, and CXCR4 were examined separately between tumor cells and stromal cells in SCC tumors." (PMID 35358193, 2022). "It has been established that the presence of immune suppressing cells, such as CD4 + FoxP3 + T regulatory cells (Tregs), in the TME can impede T cell immunity and contribute to tumor progression." (PMID 35962391, 2022). "Staining of CD8+ T cells, conventional CD4+FOXP3- T cells (Tconv cells), CD4+FOXP3+ regulatory T cells (Treg cells), CD20+ B cells, and CD68+ macrophages was performed, and cell density was evaluated in both the tumor and its stroma." (PMID 36201479, 2022). "TISIBD was employed to analyze the relationship between FOXP1, FOXP2, FOXP3, and FOXP4 and tumor-infiltrating immune cells in 28 kinds of tumor." (PMID 36203616, 2022).
tumor (continued). "Single sections underwent multiplexed immunofluorescence staining for immune cell markers (CD45, CD3, CD4, CD8, FOXP3, PD1) and tumor/cell segmentation markers (DAPI, pan-cytokeratin, AE1, NaKATPase, and S6)." (PMID 34732839, 2022). "However, the regulatory mechanism of Foxp3 in tumor cells remains unclear." (PMID 35345443, 2022). "When stained, PD-L1, Foxp3, CD8, TIA-1 were expressed diversely in tumor cells and tumor-infiltrating lymphocytes." (PMID 34275008, 2022). "To further examine the effects of PRSS2 on the immune microenvironment, we analyzed the infiltration of CD8 + and FoxP3 + T lymphocytes and their correlation with PRSS2 expression in patient tumor tissue samples." (PMID 36575174, 2022). "We also observed a similar immune cell infiltration profile in the A20 tumour model, where CAR(NAP) T-cell treatment led to higher infiltration of CD8+ T cells and Gr1+MPO+ neutrophils, and lower infiltration of FoxP3+CD4+ regulatory T cells." (PMID 35379957, 2022). "In UDCA-treated LLC tumor-bearing mice, a decrease in CD4+ CD25+ Foxp3+ Treg cells among tumor-infiltrating leukocytes (TILs) was observed." (PMID 35701426, 2022). "We observed that CD3+ FoxP3+ Tregs are prevalently distributed in the stroma and tumor-induced TLS but are rarely found in direct contact with tumor cells." (PMID 36566320, 2022). "In one patient who showed tumor regrowth 4 months after G47∆ therapy, the high numbers of CD4+ and CD8+ lymphocytes persisted whereas the number of Foxp3+ cells increased." (PMID 35864254, 2022). "In addition, loss of CAF STAT3 led to an increase in CD8+ T cells and decrease in Foxp3+ Tregs in tumor lesions, which may be a consequence of the decreased number of M2 macrophages, or alternatively indicate direct communication between CAFs and T-cell subsets." (PMID 35803738, 2022). "However, FoxP3+ cells were increased while Granzyme B+ cells were decreased, which may also reduce cancer immune surveillance and lead to increased tumor multiplicity." (PMID 36185806, 2022). "Despite an initial rise at 14 days post-tumor implantation, cytotoxic (CD3+CD8+), helper (CD3+CD4+), and Treg (CD3+CD4+FOXP3+) T-cell populations decreased by day 28 with a concordant increase in the percentage of granulocytic MDSC populations." (PMID 35626103, 2022). "Our study is the first to examine the expression of FOXP3, CD8, and CXCR4/FOXP3 in conjunction with tumor progression and prognosis in patients with conjunctival SCC." (PMID 35358193, 2022). "We also detected the expression of PD-1 and MHC class I–II in HRS cells, as well as the tumor microenvironment factors CD163 and FOXP3 in background cells." (PMID 34980000, 2022). "The expression of Foxp3 is upregulated in NSCLC and induces tumor growth and metastasis by stimulating the Wnt/β-catenin signaling pathway." (PMID 35719927, 2022). "A strong immune response to the cancer, as measured by high tumor influx of CD68(+), CD3(+) or Foxp3(+) cells, predicts better long-term overall survival, especially Foxp3(+) in HPV(+) tumor patients." (PMID 36289746, 2022). "Although the CD4+FoxP3+ Treg subset of CD4+ cells are a significant portion, CD4+FoxP3− T helper subset of T lymphocytes also have significant pro-tumour activity." (PMID 35260891, 2022). "CD8+ Teff (CTL) are immune anti-tumor effector cells whereas regulatory T cells (Treg, CD25+CD4+FoxP3+) can suppress this cytotoxic T-cell function." (PMID 36009387, 2022). "Here, we found that the high expression of PD-L2 in the stroma significantly increased the number of tumor-related CD68+ macrophages and CD4+Foxp3+ Treg regulatory T lymphocytes." (PMID 36606190, 2022). "Ex vivo, tumor infiltration by CD8+, NKp46+ and also CD4+/FoxP3+ immune cells correlated with a better outcome." (PMID 36268020, 2022). "Anti-PD-1 treatment moderately increased the tumor infiltration of CD45+CD8+ T cells and CD45+CD4+ T cells and decreased the infiltration of CD11b+Gr1+ myeloid cells and CD4+FOXP3+ Treg cells in shControl mice." (PMID 35265200, 2022).
tumor (continued). "further showed that IL4I1 stimulates the generation of Foxp3+ regulatory T cells and limits T helper 1 and T helper 2 polarization in vitro, and their findings reinforced the concept that IL4I1 facilitates tumor escape from the immune response." (PMID 36466837, 2022). "Future studies will further clarify this relationship between CD4+ FoxP3+ Tregs and cytotoxic CD8 T cells in the HNSCC tumor microenvironment following BRB-E administration." (PMID 36016924, 2022). "At the level of the TME, CRT induced a rebound effect characterized by a reduction of the T-cell anti-tumor response followed by stable radioresistant OX40 and FoxP3 Treg cell numbers." (PMID 35566403, 2022). "Correlations between frequencies of FoxP3+ Tregs and CD4+PD-1+ T cells in TME were stronger in early tumor stages, compared to advanced stages (r = 0.675, p = 0.045 [early]; r = 0.489, p = 0.089 [advanced])." (PMID 36146549, 2022). "Correlations between frequencies of FoxP3+ Tregs and CD4+TIM-3+ T cells in TME were stronger in advanced tumor stages, compared to early stages (r = 0.737, p = 0.023 [early]; r = 0.818, p = 0.0006 [advanced])." (PMID 36146549, 2022). "Our study showed increased FoxP3 expression and higher CD4+/CD8+ ratios in CD27+ tumor infiltrating lymphocytes surrounding CD70+ tumor cells in NSCLC patients." (PMID 34991665, 2022). "We adopted multiplex immunofluorescence labelling of CD4+ T cells, Tregs (T regulatory cells CD4+, Foxp3+), CD8+ T cells, and B cells (B220+), at 12 weeks and ethical endpoints in the mouse APs tumours (respectively)." (PMID 36075907, 2022). "Our analysis then indicated that metastasis LN exhibited an early activated tumor microenvironment (TME) characterized by the decrease of naive T cells and an increase of cytotoxicity CD8 T cells, NK cells, FOXP3+ Treg cells compared with normal LN." (PMID 36569924, 2022). "The number of CD8+, FOXP3+, CD68+, CD163+ and PMNs was highly variable, however, all immune cells prevailed in stroma when compared to tumor nests." (PMID 35681497, 2022). "In a recent publication, the immune cell infiltrations (CD3+, FOXP3+, CD8+ T cells, CD20+ B cells) and expressions of PD-1, PD-L1 and IDO1 were evaluated in a cohort of 162 OCCC tumours on a tissue microarray by multiplex immunohistochemistry." (PMID 35043008, 2022). "Piezo1-/- mice had more Foxp3+ Treg cells, fewer IFNγ+ TH1 cells, and normal numbers of TH2, TH17, CD8+T cell, and IFNγ+CD8+T cells in tumor tissue compared with WT control." (PMID 35993548, 2022). "Most current reports consider CD8+T cells, FOXP3+T cells, and CD68+ macrophages to be the primary innate immune response in the tumor microenvironment." (PMID 36011316, 2022). "CD8+ T cells appeared in closer proximity to tumor cells, CD163+ macrophages and FoxP3+ cells in HPV-positive primary tumors, and related metastases." (PMID 36123711, 2022). "FOXP3 and CD8 protein expression were quantified by counting the positive cells in relation to all cells (tumor, immune and other cells) in the tissue section." (PMID 34125345, 2022). "It has been confirmed that drug therapy plays a role in remodeling the tumor immune microenvironment, such as decreased density of CD8+ cells and increased density of FoxP3+ cells and B cells (CD20+) in PTs after NAC, but PD-L1 expression did not change." (PMID 36225938, 2022). "Foxp3 induces EMT, tumor metastasis and growth, and reduces overall and recurrence-free survival, thereby worsening the prognosis." (PMID 35719927, 2022). "We observed that Mito‐ATO significantly increased tumor infiltrating CD4+ T cells, and also resulted in a significant reduction of G‐MDSCs and Foxp3+ Tregs within tumors receiving Mito‐ATO treatment." (PMID 35243806, 2022).
tumor (continued). "FOXP3 increases the expression of CD25 and CTLA4 and reduces tumor immunity by suppressing the production of effector cytokines such as IL-2, IFNγ, IL-4, and IL-17." (PMID 36132149, 2022). "The number of tumor-infiltrating CD4+, CD8+, Foxp3+lymphocytes, CD68+, CD163+macrophages in pre-treatment endoscopic biopsy samples were evaluated to investigate their predictive value for multidisciplinary treatment." (PMID 35658848, 2022). "First, we compared the internal areas of the primary tumor and liver metastases, found that 8 markers (CD8, Foxp3, CD68, CD163, CD20, CD11c, VEGFR-2, PD-L1) had higher expression in TF than TC region in both primary tumor and liver metastases (p < 0.05)." (PMID 36195882, 2022). "who reported respectively Foxp3+ T cell-rich TLS in colorectal cancer and CD8+-T reg and Th2 cells circling tumor cells in Hodgkin lymphoma." (PMID 35432353, 2022). "Since CD8+, PD‐1+, and FOXP3+ TAICs were correlated, the combined mean density of CD8+, FOXP3+, and PD‐1+ TAICs was calculated for the tumor epithelium and tumor stroma compartments, as a surrogate marker for general T‐cell infiltration." (PMID 34743329, 2022). "A remarkably decreased number of FoxP3-expressing and IL-10-producing CD4+ Tregs were observed in the tumors of 4T1+d-MAPPS-treated animals compared to tumor-bearing animals that received saline (p < 0.05)." (PMID 35757015, 2022). "FOXP3+ cells were seen in the vicinity of CCL22-positivity, which had a punctate pattern throughout the tumor." (PMID 35025968, 2022). "CD8+, FOXP3+, and PD‐1+ TAIC densities were positively correlated in both the tumor epithelium and the tumor stroma compartment, suggesting a general T‐cell infiltration." (PMID 34743329, 2022). "SPI1 expression was positively and strongly associated with T cell exhaustion markers (LAG3 and PDCD1,), and Treg cell markers (FOXP3 and CCR8), suggesting that high SPI1 expression level inhibits anti-tumor immunity." (PMID 36477668, 2022). "In contrast, the Gr-1 and FoxP3 signals were only slightly influenced in the DOX group, possibly due to the poor tumor-targeting and insufficient ICD-inducing ability of free DOX." (PMID 36319625, 2022). "Using enzymatic double-staining immunohistochemistry, we analysed CD8 + PD-1+ TILs and CD4 + FoxP3+ TIL counts in the stroma and intra-tumour in nine ICC patients selected based on high TILs in hematoxylin and eosin staining." (PMID 35597869, 2022). "The densities of CD3+CD4+ cells (CD4+ T cells), CD3+CD8+ cells (CD8+ T cells), CD4+Foxp3+ cells (Treg cells), and CD204+ cells were compared with the patients’ background tumor characteristics." (PMID 35462552, 2022). "Alongside TNFRSF4/OX40 and TNFRSF9/4-1BB, we selected a number of markers of tumor-resident Tregs (CTLA4, ICOS, TIGIT, and FOXP3) and performed k-means clustering for all UPS, MFS, and DDLS samples in the TCGA." (PMID 35558159, 2022). "Immunohistochemistry of tumor tissues revealed a strong co-expression between HIF-1α, Foxp3 and TGF-β." (PMID 35625561, 2022). "The IHC staining of CD8+ T cells, CD4+T cells, NK1.1+ NK cells, CD68+TAM, FOXP3+Treg cells and CD11C+ DCs in the tumor tissues also showed a similar trend." (PMID 35525959, 2022). "To specifically define the role of KLRG1 on NK cells or Tregs in a variety of murine tumor models, we have begun to cross KLRG1 floxed mice to Ncr-Cre and Foxp3-Cre respectively." (PMID 35572605, 2022). "To validate our findings, we carried out IHC staining of all the primary tumour samples using a customised in house immune panel to evaluate the presence of CD3+, CD8+, CD163+, FOXP3+ and PD-L1+ cells." (PMID 36253523, 2022). "We also analyzed tumor CD3+, CD4+, and CD8+ T-cell and FOXP3+ cell percentages via immunofluorescence staining." (PMID 36212401, 2022).